MIR422A (microRNA 422a)
Synonyms: hsa-mir-422a; MIRN422A
Gene: MicroRNA gene on chromosome 15 (63,870,930 to 63,871,019, reverse strand). Ensembl gene ENSG00000199156.
Gene Ontology:
Biological process: miRNA-mediated post-transcriptional gene silencing
Homologues: Orthologues: chimpanzee ptr-mir-422a (100% identical), macaque mml-mir-422a (94% identical).